MUC16 (mucin 16, cell surface associated)
Diseases named in the same sentence as MUC16 in open-access papers (continued):
Sharing a sentence is not in itself a finding about the gene and the disease.
benign tumors (7 papers, 2009 to 2025). "The results showed that MUC16 mutation and a lower immune response were associated with reduced RFS in lymph node‐positive ESCC." (PMID 38733174, 2024). "Of these, 15 proteins (PRSS8, MK, WFDC2 (HE4), IL-10, SOD2, PARP-1, hK11, PVRL4, MUC-16 (CA125), FR-alpha, CDH3, NTRK3, IL-8, IL-17C, EN-RAGE) were selected from the comparison between OC stage I–IV and benign tumors." (PMID 30519148, 2018).
gastrointestinal tumor (4 papers, 2018 to 2024). "Thus, the eight gene panel (CXCL12, CK7, CDH1, CTNNB1, CD44v6, MUC16, TGFBR2 and HIF1A) can be a highly significant predictor of liver metastasis outcome independent of the standard prognostic criteria." (PMID 30383826, 2018).
bacterial infections (3 papers, 2021 to 2025). "Second, the Basal.MUC16 cluster showed a significant increase (adjusted p < 0.05) in genes associated with bacterial infection (PDZD3, SFTPA2, PIK3C2B), cytokine signaling (TRIM31, SERPINB2), and apoptosis (BCL2L15, VIL1)." (PMID 39935174, 2025). "Similarly, the higher presence in S/SEV_FREE of MUC 5, MUC7, and MUC16 may indicate a condition in which the oral mucosa of OSCC_FREE subjects is more protected from bacterial infections that are strictly related to oral carcinogenesis." (PMID 34681822, 2021). "MUC16 was not significantly altered by any of the tested bacterial infections." (PMID 34903740, 2021).
gynecological tumor (2 papers, 2016 to 2020). "Finally, the glycoproteins MUC16 and WFDC2 are two proteins widely evaluated, since their high expression demonstrated either diagnostic and prognostic value in gynecological tumors." (PMID 32560580, 2020).
peripheral neuropathy (1 paper, 2025). A disorder affecting the peripheral nervous system. "DMUC5754A showed an acceptable safety profile, with main adverse events being fatigue, peripheral neuropathy, and nausea, and demonstrated early anticancer activity, especially in patients with high MUC16 expression." (PMID 40722601, 2025).
MUC16 also shares sentences with these, for which no sentence is quoted: lung squamous cell carcinoma (5 papers); peritoneal carcinoma (5); tuberculosis (4); adenomyosis (3); anemia (3); B-cell lymphomas (3); cyst (3); liver (3); brain cancer (2); chronic heart failure (2); endometrioid tumor (2); goblet cell adenocarcinoma (2); Hepatic fibrosis (2); Hypertension (2); Hypoalbuminemia (2); idiopathic pulmonary fibrosis (2); lymphoma (2); mucinous ovarian tumors (2); pneumothorax (2); systemic lupus erythematosus (2); testicular cancer (2); thymoma (2); thyroiditis (2); abscess (1); acromegaly (1); acute myocardial infarction (1); Allergy (1); angiosarcoma (1); atrial fibrillation (1); biliary tract cancer (1).
A further 101 diseases each share a sentence with MUC16 in 1 paper.